HLA-DRB1 (major histocompatibility complex, class II, DR beta 1)
Diseases named in the same sentence as HLA-DRB1 in open-access papers (continued):
Sharing a sentence is not in itself a finding about the gene and the disease.
gastric diseases (2 papers, 2016 to 2018). "The HpaA88-100 specific CD4+ T cell response was found to be associated with resistance to severe gastric diseases correlated to H. pylori infection in HLA-DRB1*1501 positive subjects." (PMID 27509059, 2016). "The immunodominant CD4+ T cell responses specific to HpaA88-100 were observed in most H. pylori infected individuals who expressed HLA-DRB1*1501 and were significantly more abundant in patients with less severe gastric diseases." (PMID 27509059, 2016).
Giardia infection (2 papers, 2021 to 2022). "Moreover, Case 4 has the HLA-DRB1*13:01 allele, which has been previously associated with susceptibility to Giardia infection." (PMID 36498582, 2022). "First, four MHC class II alleles were chosen, the MHC class II I-Ak and I-Ad that are expressed in mice widely used as model for giardiasis, as well as the HLA-DRB1 * 03: 01 and HLA-DRB1 * 13: 01 alleles that are related to an increased risk of G. lamblia infection." (PMID 34778111, 2021).
hemophilia A (2 papers, 2012 to 2013). The most common form of hemophilia characterized by spontaneous or prolonged hemorrhages due to factor VIII deficiency. "An increased occurrence of FVIII inhibitor was reported in cases of severe congenital hemophilia A with HLA-DRB1*15:01, DQA1*01:02,and DQB1*06:02 alleles." (PMID 24744621, 2012). "In addition, another six peptides described in this paper were recently identified as epitopes in a novel human HLA-DRB1*1501 transgenic mouse model for hemophilia A." (PMID 24244658, 2013).
Hepatic fibrosis (2 papers, 2018 to 2026). The presence of excessive fibrous connective tissue in the liver. "We evaluated whether HLA-DRB1, PNPLA3, SLCO1B1, and MTHFR variants are associated with NAFLD, liver fibrosis, or MTX toxicity/pharmacokinetics in RA, after accounting for clinical covariates." (PMID 41753255, 2026).
inclusion body myositis (2 papers, 2019 to 2020). A slowly progressive degenerative inflammatory disorder of skeletal muscles characterized by late onset weakness of specific muscles and distinctive histopathological features. "Sporadic inclusion body myositis is an acquired disease, yet genetic predisposition to IBM involving the Human Leukocyte Antigen—DR isotype β1 (HLA-DRB1) genotype has been described." (PMID 30621041, 2019).
lepromatous leprosy (2 papers, 2009 to 2025). A chronic communicable infection which is a principal or polar form of leprosy. "In the case of Mycobacterium leprae, the pathogen responsible for lepromatous leprosy, its association with HLA-DRB1*15:01 promotes a Th2-type immune response characterized by excessive IL-10 and TGF-β production at foci of infection." (PMID 41425584, 2025). "Jørgen leprosarium (Odense, Denmark) showed that the allele HLA-DRB1*15:01, rather than conferring protection, was significantly associated with increased susceptibility to lepromatous leprosy, similar to observations in modern populations in India, China, and Brazil." (PMID 41425584, 2025).
lung adenocarcinoma (2 papers, 2022 to 2024). A carcinoma that arises from the lung and is characterized by the presence of malignant glandular epithelial cells. "The top genes of activated neutrophils, namely HLA‐DPA1, HLA‐DRA, and HLA‐DRB1, were found to be associated with a good prognosis in lung adenocarcinoma (LUAD)." (PMID 38483933, 2024). "The present case was a lung adenocarcinoma with an ALK-HLA-DRB1 fusion, which consisted of exon 20 of the ALK gene and exon 8 of the HLA-DRB1 gene." (PMID 35280798, 2022). "And two cases of lung adenocarcinoma being driven by a HLA-DRB1-MET gene rearrangement with an excellent response to crizotinib." (PMID 35280798, 2022). "Here, we describe a case of advanced lung adenocarcinoma harboring a rare ALK-HLA-DRB1 (major histocompatibility complex, class II, DR beta 1) gene fusion." (PMID 35280798, 2022). "There have been 4 described cases of HLA-DRB1-MET gene rearrangement in lung adenocarcinoma." (PMID 35280798, 2022).
Lyme borreliosis (2 papers, 2012 to 2016). "The aim of this study was to identify disease-associated HLA-DRB1 alleles in Latvian patients with Lyme borreliosis and Lyme neuroborreliosis." (PMID 27916969, 2016). "Probably, only HLA-DRB1*11 allele (9.8 percent vs. 3.9 percent; odds ratio 0.38; pc = 0.006) has a protective effect in the pathogenesis of Lyme disease." (PMID 27916969, 2016). "Only the HLA-DRB1*07 allele was statistically significant after applying the Bonferroni correction associated with Lyme neuroborreliosis in Latvian patients (odds ratio 2.97; pc = 0.041)." (PMID 27916969, 2016). "The majority of individuals with Lyme disease have the HLA-DRB1*0401 or HLA-DRB1*0101 allele, alleles which also occur more frequently in patients with RA." (PMID 22892251, 2012).
lymphopenia (2 papers, 2023 to 2025). Reduction in the number of lymphocytes. "Rather, they provide a basis for future studies on the connection between HLA-DRB1*07 and PB lymphopenia mechanisms." (PMID 37161980, 2023). "Thus, we think our finding that the majority of HLA-DRB1*07 positive patients belonged to the PB lymphopenia group deserves further attention." (PMID 37161980, 2023). "Insight into the influence of HLA-DRB1 alleles, bronchoalveolar fluid (BALF) cells and patient phenotype on PB lymphopenia may provide mechanistic clues and help to disentangle immunological mechanisms behind." (PMID 37161980, 2023). "Thus, it is tempting to speculate that patients with lymphopenia and/ or HLA-DRB1*07 positive patients should receive 3rd line treatment with TNF-α inhibitors early in disease course without first trying 1st and 2nd line treatments." (PMID 37161980, 2023). "HLA DRB1*07 was more common in patients with lymphopenia than in patients without lymphopenia (P = 0.001), 67% of HLA-DRB1*07 carriers had lymphopenia at diagnosis." (PMID 37161980, 2023).
male infertility (2 papers, 2016 to 2022). The inability of the male to effect fertilization of an ovum after a specified period of unprotected intercourse. "For HLA-DRB1, immunoinfertility belongs to the associated phenotypes listed in the Male Infertility Knowledgebase." (PMID 36613967, 2022). "Most SNP-populated genes related to male infertility include HLA-DQB1 (20 SNPs), HLA-DRB1 (15 SNPs), MTHFR (10 SNPs), BRCA2 (9 SNPs), ACE (8 SNPs), CFTR (6 SNPs), CDH1 (6 SNPs), SRD5A2 (6 SNPs), HLA-DQA1 (5 SNPs) and MMP9 (5 SNPs)." (PMID 29263816, 2016).
MODY (2 papers, 2017 to 2019). "In this case, the comparison of each of the HLA-DRB1 genotypes versus the remaining categories, showed that the frequency of genotypes with two risk alleles was significantly lower in MODY than in patients with autoimmune diabetes, OR 0.06 (95% CI: 0.02–0.18)." (PMID 28052112, 2017). "Furthermore, the HLA-DRB1 genotype distribution is similar between MODY and control subjects." (PMID 28052112, 2017). "In these particular cases, neither clinical data nor HLA-DRB1 helped to differentiate MODY." (PMID 31365591, 2019).
multiple myeloma (2 papers, 2018). "LB-ACBA5-1R specific CD4 T-cells were incubated with myeloma cell-lines UM-6 and RPMI8226 transduced with HLA-DRB1*11:01." (PMID 30619360, 2018).
ocular sarcoidosis (2 papers, 2023 to 2024). A leading cause of inflammatory eye disease is sarcoidosis. "While the HLA-DRB1*0401 and MAGI1 genes represent susceptibility to ocular sarcoidosis." (PMID 39598118, 2024).
optic neuritis (2 papers, 2021 to 2025). Optic neuritis is inflammation of the optic nerve, the nerve that carries the visual signal from the eye to the brain.The conditionmay cause sudden, reduced vision in the affected eye(s). "The analysis showed that a significant link between optic neuritis in MS patients and HLA-DRB1 * 15:01 and HLA-DQB1 * 06:01 alleles compared to MS group without optic neuritis." (PMID 39999097, 2025). "While in other MS populations in the Netherlands and India demonstrated that HLA-DRB1 * 03:01 allele is linked with optic neuritis." (PMID 39999097, 2025). "Several HLA class II alleles has also been shown to be associated with optic neuritis, such as HLA-DRB1 * 16:02 in China and HLA-DRB1 * 04:05 in South Brazil." (PMID 39999097, 2025). "The HLA-DRB1 * 03:01, HLA-DRB1 * 11:01, and HLA-DRB1 * 15:01 alleles were the most frequently observed in MS patients who have optic neuritis." (PMID 39999097, 2025). "HLA-DRB1*15:01 was associated with increased optic neuritis and cerebellar involvement and worsened visual and pyramidal functional scale (FS) scores, resulting in higher progression index values." (PMID 33436735, 2021). "HLA-DRB1*04:05 was associated with younger onset age, high visual FS scores, and a high tendency to develop optic neuritis." (PMID 33436735, 2021). "In addition, our results revealed strong association between HLA-DRB1 * 15:01 allele and MS with optic neuritis." (PMID 39999097, 2025). "In addition, a significant linkage between HLA-DRB1 * 15:01 and HLA-DQB1 * 06:01 alleles (Pc ≤ 0.001 and Pc = 0.012, respectively) were presented among Jordanian MS patients with optic neuritis compared to Jordanian MS patients without optic neuritis." (PMID 39999097, 2025).
osteoarthritis (2 papers, 2014 to 2022). A noninflammatory degenerative joint disease occurring chiefly in older persons, characterized by degeneration of the articular cartilage, hypertrophy of bone at the margins and changes in the synovial membrane. "HLA-DRB1, CD74 and APOL4 were also found previously to be induced by IFN-γ in osteoarthritis chondrocytes." (PMID 35326396, 2022).
pancreatic cancer (2 papers, 2025). "We developed an in vitro stimulation approach and identified HLA-A*11:01–restricted KRAS G12V–reactive CD8+ T cells and HLA-DRB1*15:01–restricted KRAS G12V–reactive CD4+ T cells from peripheral blood of 2 out of 6 HLA-A*11:01–positive patients with pancreatic cancer whose tumors expressed KRAS G12V." (PMID 39846249, 2025).
panic disorder (2 papers, 2016 to 2022). An anxiety disorder characterized by multiple unexpected panic attacks with persistent concern of recurring attacks. "HLA-B and HLA-DRB1 were investigated as candidate susceptibility genes for panic disorder in 744 subjects and 1418 control subjects." (PMID 36231907, 2022). "We herein report an association between TMEM132D and panic disorder (PD) in a Japanese population, evaluating the effects of HLA-DRB1*13:02, which we previously reported as a susceptibility genetic factor for PD." (PMID 27081567, 2016). "The study provided the initial evidence that the HLA-DRB1*13:02 allele is associated with panic disorder, but without clarifying the mechanisms that determine this." (PMID 36231907, 2022).
peanut allergies (2 papers, 2024). "The peptides identified in the present study offer potential for epitope-based immunotherapy targeting HLA-DRB1*03:01-restricted peanut allergy patients, potentially reducing the risk of irrelevant protein targeting and minimizing undesirable immune responses." (PMID 39204201, 2024). "Studies have identified a potential link between peanut allergy and certain HLA alleles, such as HLA-DRB1*08, DQB1*04, DQB1*06:03, and HLA-DRB1*03:01." (PMID 39204201, 2024). "Here, we applied an immunoinformatic approach to derive a model for the prediction of peptides binding to HLA-DRB1*03:01, one of the HLA alleles susceptible to peanut allergy." (PMID 39204201, 2024). "Here, the method was applied to derive a logo model for peptide binding predictions to one specific HLA allele, namely HLA-DRB1*03:01, which is associated with peanut allergy." (PMID 39204201, 2024). "The study showed that rs9275596 was a meQTL for the HLA-DRB1 and HLA-DQB1 genes, and that methylation was associated with risk of peanut allergies." (PMID 39355248, 2024).
pemphigus foliaceus (2 papers, 2012 to 2020). Pemphigus foliaceous is a rare superficial pemphigus disease characterized by multiple, pruritic, scaly, crusted cutaneous erosions, with flaky circumscribed patches, localized mostly on the face, scalp, trunk and extremities, often presenting an erythematous base. "The associations of pemphigus foliaceus with Bw4 and with HLA-DRB1 might both result from their functions." (PMID 22768326, 2012). "Analysis of polymorphic residues that form the binding pockets of the DRβ1 chain of HLA-DRB1*04 and *14 alleles in pemphigus vulgaris show that they contain similar sequences, as well as in HLA-DRB1*04, *14 and *01 in pemphigus foliaceus." (PMID 33584677, 2020).
Periodontal diseases (2 papers, 2016 to 2025). "The study results indicate that the HLA-DRB1*03 and HLA-DRB1*15 haplogroups may predispose Brazilian patients with T1D to advanced forms of periodontal disease." (PMID 40283738, 2025).
plague (2 papers, 2021 to 2022). Plague is a severe bacterial infection caused by the gram-negative bacterium Yersinia pestis. "The HLA-DRB1*13 allelic group increased in frequency from 5.6% in the plague victims to 17% in the modern Ellwangen individuals and 12% in the German bone marrow donors, potentially indicating antibody-driven protection from the plague for individuals having this allotype." (PMID 34002224, 2021).
podoconiosis (2 papers, 2012 to 2013). A disease of the lymphatic vessels of the lower extremities that is caused by chronic exposure to irritant soils. "The present study and a previous one also showed that the frequencies of HLA-DQB1*02 (a risk allele for podoconiosis) and HLA-DRB1*13 (a protective allele against podoconiosis) in the Ethiopian population were among the highest in Sub-Saharan Africa." (PMID 22761960, 2012).
preeclampsia (2 papers, 2017 to 2023). Preeclampsia is a hypertensive disorder of pregnancy that is characterized by new-onset hypertension with proteinuria presenting after 20 weeks of gestation, and depending on mild or severe forms may initially present with severe headache, visual disturbances, and hyperreflexia. "Mismatches in HLA-B eplets: 65QIA+76ESN, 70IAO, 180E, HLA-C eplets: 193PL3, 267QE, and HLA-DRB1 eplet: 16Y were associated with a mild outcome of preeclampsia if the complication occurred." (PMID 38022600, 2023). "Recent work in preeclampsia has focused on the role of T cells and adaptive immunity in preeclampsia; both HLA-A and HLA-DRB1 identified from this study are involved in the biology of T cells." (PMID 28130428, 2017). "While significant changes in circulating HLA-A were not supported by changes in placental tissue, another gene of interest identified from the microarray, HLA-DRB1, was significantly upregulated in placental tissue from women with preeclampsia." (PMID 28130428, 2017). "In placenta of women with preeclampsia we identified that HLA-DRB1 is upregulated." (PMID 28130428, 2017). "While general trends were preserved, only HLA-A was validated in whole blood samples from cases using qPCR (2.30- ± 0.9-fold change) whereas in placental tissue HLA-DRB1 expression was found to be significantly increased in samples from women with preeclampsia (5.88- ± 2.24-fold change)." (PMID 28130428, 2017). "However, expression of HLA-DRB1 was significantly increased in placental tissue from women with preeclampsia (fold change: 5.88 ± 2.24)." (PMID 28130428, 2017). "While neither HLA-A or HLA-DRB1 has been previously reported in these studies, genes involved in the immune response have been shown to be differentially expressed in women with preeclampsia." (PMID 28130428, 2017).
primary sclerosing cholangitis (2 papers, 2016 to 2021). "Similarly, HLA-DRB1 polymorphisms lead to differential electrostatic charges of binding pocket 9 and are thus related to the susceptibility to primary sclerosing cholangitis." (PMID 33917549, 2021). "Significantly higher frequency of HLA-DRB1*15 was reported in primary sclerosing cholangitis patients with increased levels of IgG424." (PMID 27934873, 2016).
rhabdomyolysis (2 papers, 2022 to 2025). Necrosis or disintegration of skeletal muscle often followed by myoglobinuria. "Genetic data suggest an increased susceptibility to rhabdomyolysis in individuals of Japanese descent, due to specific mutations in genes involved in muscle metabolism, such as HADHA, HADHB, CACNA1S, and HLA-DRB1* 04:06." (PMID 40709115, 2025).
sarcopenia (2 papers, 2020 to 2025). Progressive decline in muscle mass due to aging which results in decreased functional capacity of muscles. "Two HLA types, HLA-DQA*03:01 (p = .032) and HLA-DRB1*04:04 (p = .038), were nominally associated with sarcopenia (EWGSOP’s combined definition), indicating that the effect of these HLA types is significantly greater in females, compared to males." (PMID 30772894, 2020). "MMP24‐AS1, HLA‐DRB6, HLA‐DQA2, DDX42, BAG6, NUSAP1, LINC00940, NME1‐NME2 and AS3MT in the amygdala region showed detrimental effect on all the five sarcopenia‐related traits, whereas HLA‐DRB1, HLA‐DQB1‐AS1 and C6ORF3 showed protective effect (p < 0.05)." (PMID 39535371, 2025). "The over‐expression of nine genes (MMP24‐AS1, HLA‐DRB6, HLA‐DQA2, DDX42, BAG6, NUSAP1, LINC00940, NME1‐NME2 and AS3MT) in the amygdala region showing detrimental effect on all the five sarcopenia‐related traits, whereas three genes (HLA‐DRB1, HLA‐DQB1‐AS1 and C6ORF3) showing protective effect." (PMID 39535371, 2025). "Analysis of non-coding variants within the HLA region, which are involved in the expression and regulation of HLA (HLA-DRB1, HLA-DQA2), and the Endoplasmic Reticulum unfolded protein stress response (AFT6B), has shown an association with these variants and sarcopenia." (PMID 30772894, 2020).
squamous cell carcinoma (2 papers, 2017 to 2021). A carcinoma arising from squamous epithelial cells. "As with squamous cell carcinoma, risk associations were seen between adenocarcinoma and HLA Class I (HLA-B*0702 (OR = 1.48, P = 2.65 × 10−5)) and Class II (HLA-DRB1*15 (OR = 1.49, P = 0.00012; HLA-DQB1*0602 (OR = 1.48, P = 0.00026) alleles." (PMID 28806749, 2017). "For squamous cell carcinoma, the strongest risk HLA allele associations were seen with HLA-DQB1*0602 (OR = 1.52, P = 1.47 × 10−7) and HLA-DRB1*1501 (OR = 1.50, P = 2.95 × 10−7)." (PMID 28806749, 2017). "A reduced risk of squamous cell carcinoma was seen with both HLA Class I (HLA-B*15 (OR = 0.55, P = 4.78 × 10−6)) and HLA Class II alleles (HLA-DQA1*0103 (OR = 0.69, P = 0.006), HLA-DRB1*13 (OR = 0.71, P = 5.27 × 10−4), HLA-DQB1*0603 (OR = 0.69, P = 0.007))." (PMID 28806749, 2017). "In addition to the strong reduced risk of cervical neoplasia associated with HLA-B*15, the haplotype HLA-DRB1*1301/HLA-DQB1*0603 (and in some analyses HLA-DQA1*0103) was associated with reduced risk of squamous cell cancer, adenocarcinoma, and HPV16- and HPV18-related cervical neoplasia." (PMID 28806749, 2017).
staphylococcus aureus infection (2 papers, 2018 to 2021). An infectious process in which the bacteria Staphylococcus aureus is present. "Target DEGs of differentially expressed miRNAs were significantly enriched in staphylococcus aureus infection involving four DEGs (HLA-DRB1, HLA-DRB5, C3, and ICAM), which suggested that inflammation may be a factor for STC." (PMID 30186855, 2018). "Among which, we also performed the PPI network of several DEGS including C3, HLA-DRB5, ICAM1 and HLA-DRB1, ITGAM, and CFD that involved in the staphylococcus aureus infection signaling pathway." (PMID 30186855, 2018). "HLA-DRB1, HLA-DRB5, C3, and ICAM were significantly involved in staphylococcus aureus infection." (PMID 30186855, 2018).
Stroke (2 papers, 2019 to 2024). Sudden impairment of blood flow to a part of the brain due to occlusion or rupture of an artery to the brain. "The expression of HLA-DRB1 and HLA-DQB1 was lesser in stroke patients than in normal controls (P < 0.05)." (PMID 31527307, 2019).